IL10 (interleukin 10)
Diseases named in the same sentence as IL10 in open-access papers (continued):
Sharing a sentence is not in itself a finding about the gene and the disease.
leprosy (continued). "We also observed the change in the phenotype of Teff and Tregs under the influence of IL-10 producing Bregs and enhanced regulatory T-cells function in human leprosy." (PMID 30083152, 2018). "In conclusion, our study evidently demonstrates that IL-10 secreting Bregs are a functionally distinct cell subset that influences the fate of T cells in leprosy patients." (PMID 30083152, 2018). "Results from numerous studies have shown that IL-10 secreted by different cells play an important role for the pathogenies of leprosy." (PMID 30083152, 2018). "The IFN-β response can induce IL-27-dependent IL-10 activation, which in leprosy, is a well-known immune suppressive mechanism that favors mycobacterial growth and dissemination." (PMID 29755459, 2018). "Our results collectively show that IL-10 producing Bregs increased from BT to BL/LL pole of leprosy patients and suggesting an immunomodulatory role of these Bregs." (PMID 30083152, 2018). "To model the MΦ subtypes in leprosy lesions, we studied MΦ subsets derived in vitro with IL-15- vs. IL-10-treated monocytes yielding M1-like vs. M2-like MΦ, respectively." (PMID 30300363, 2018). "Cell coculture experiments also demonstrated that leprosy derived IL-10 producing Bregs enhance FoxP3 and PD-1 expression in Tregs and enhanced Tregs activity." (PMID 30083152, 2018). "This indicates that by refuting the influence of immunosuppressive IL-10 cytokine we can successfully restore the beneficial effector T cells response and limit the Tregs activity in leprosy patients." (PMID 30083152, 2018). "Our data have indicated that a population of B cells in the leprosy patients constitutively produced IL-10 (Bregs) and this population was greater in abundance in the lepromatous leprosy (BL/LL)." (PMID 30083152, 2018). "The phagocytic program induced in macrophages by IL-10 is most apparent in leprosy patients that progress to the extreme LL clinical form." (PMID 28162092, 2017). "The first two cytokines are known to be important in leprosy immune reactivation, while IL-10 is correlated with the pathogenesis of multibacillary forms." (PMID 27764137, 2016). "We identified higher serum IL-1, IL-6, and IL-10 levels in individuals with leprosy and dental infection compared with individuals with leprosy without dental infection." (PMID 26339136, 2015). "IL-10 up-regulation can suppress lymphocyte-driven immunity, and in leprosy IL-10 is detected in multibacillary lesions." (PMID 25210773, 2014). "To evaluate the combined diagnostic value of IL-10, IP-10 and IFN-γ, we first determined their concentrations by ELISAs in 24 h WBA of 11 Ethiopian leprosy patients (9 BL, 2 BT) and 12 EC." (PMID 24810599, 2014). "Since short overall test-to-result times are preferred for diagnostic assays, the supernatants of WBA of Ethiopian leprosy patients and EC were analyzed for the presence of IFN-γ, IL-10 and IP-10 after 1 h, 4 h, 6 h and 24 h stimulation." (PMID 24810599, 2014). "Early studies of leprosy intradermal cytokine expression determined that leprosy polarity is associated with TH2 cytokines IL4, IL5, IL10 in lepromatous lesions, and TH1 polar cytokines, IFNG, IL2, in tuberculoid lesions." (PMID 25412496, 2014). "The combined diagnostic value of IP-10, IL-10 and anti-PGL-I antibodies was tested using M. leprae-stimulated blood of leprosy patients and endemic controls (EC)." (PMID 24810599, 2014). "This has been confirmed by the observation that polymorphisms of key cytokines genes, such as TNF, IL-12, IL-4, IL-10, TGF-B, IL-6, and their respective receptors have been associated with susceptibility to and severity of leprosy." (PMID 24498610, 2013). "The results of these studies strongly suggest the involvement of SNPs in the promoter region of the IL10 gene in leprosy." (PMID 23936864, 2013). "In case-control studies, SNPs in the IL10 gene (−819 C>T) and IFNG gene (+874 T>A) were reported to be associated with susceptibility and protection in leprosy, respectively." (PMID 23798993, 2013).
leprosy (continued). "In Schwann cells, M. leprae infection-induced biogenesis of lipid droplets correlates with increased prostaglandin E2 (PGE2) and interleukin-10 (IL-10) secretion, which is essential for leprosy pathogenesis." (PMID 23236531, 2012). "Additionally, our focus on three cytokines (IFN-γ, IL-12, and IL-10) restricts understanding of the broader cytokine network involved in leprosy-STH interactions." (PMID 40636115, 2025). "Analysis of IL-10-producing FoxP3+ Tregs in different polar forms and healthy controls revealed that the number of Tregs in patients was twice that of healthy contacts, and leprosy LL/BL patients also exhibited significantly higher Treg numbers." (PMID 38440733, 2024). "Furthermore, Treg cells produce significant amounts of IL-10 in leprosy patients, indicating that these cells are suppressive in nature." (PMID 37153623, 2023). "Patients with co-infections had decreased levels of IFN-γ, a Th1 cytokine, and increased levels of IL-4 and IL-10, Th2 cytokines, suggesting that co-infection might facilitate the development of disseminated leprosy." (PMID 37216331, 2023). "IL-10 has also been described in the lepromatous pole of leprosy." (PMID 38116016, 2023). "However, there is significant difference in IL-10 level upon PD-1 blocking in both groups of leprosy patients." (PMID 37153623, 2023). "Elucidating the sources of IL-10 in LL could shed light on the mechanism of T cell regulation in leprosy." (PMID 35867720, 2022). "We further select 7 cytokines and immune mediators to detect immune response after vaccination and found that before the onset of vaccination, leprosy cured group have relatively high concentration of IL-6, IL-10, TNF, INF-γ and IL-17 compared to control group." (PMID 34397815, 2021). "Here, we investigated whether SNPs located in eleven genes: CCDC122/LACC1, IFNG, IL6, IL10, IL23R, LRRK2, NOD2, PACRG/PRKN, TLR1, TNF and TYK2 are associated to leprosy susceptibility in a population in the North of Brazil." (PMID 32433683, 2020). "Distribution of IL-10 (G/A at −1082: rs1800896) genotypes in leprosy patients and control subjects." (PMID 32849660, 2020). "Distribution of IL-10 (C/T at −819: rs1800871) genotypes in leprosy patients and control subjects." (PMID 32849660, 2020). "We want to address the source of IL-10 production by various genotypes in leprosy patients." (PMID 32849660, 2020). "Moreover, CD19+ B cells of leprosy patients (BL/LL) also induces FoxP3, PD-1 expression as well as also induced IL-10 and TGF-β immunosuppressive cytokines expression in T effector cells." (PMID 30083152, 2018). "Our findings may pave way for novel targets of IL-10 producing Bregs for immunotherapy in leprosy patients." (PMID 30083152, 2018). "Nonetheless, follow-up of one patient suggested that IL-10–mediated regulatory responses induced during leprosy may help control the immunopathology of mucosal leishmaniasis." (PMID 29494584, 2018). "We first analyzed the frequency of IL-10-producing B cells in the PBMCs of healthy controls and leprosy patients to determine whether Mycobacterium leprae infection induces Breg response in leprosy patients." (PMID 30083152, 2018). "Furthermore, Diniz and colleagues reported the decrease of interferon-γ and the increase of Th2 cytokines IL-4 and IL-10 levels in lepromatous leprosy patients co-infected with STH." (PMID 27278453, 2016). "It was previously proposed that a balance between IFN-γ, TNF, and IL-10 could be useful either to the determination of protective immunity or to leprosy pathogenesis." (PMID 25992795, 2015). "This M. leprae-induced IL-10 could contribute to the development of the T cell anergy seen at the Th2-dominant lepromatous end of the leprosy spectrum by steering the immune response toward a phagocytic rather than antimicrobial program." (PMID 25210773, 2014).
leprosy (continued). "The role of IL-10 in resistance and inflammation in leprosy was investigated using Mycobacterium leprae infection of mice deficient in IL-10 (IL-10−/−), as well as mice deficient in both inducible nitric oxide synthase (NOS2−/−) and IL-10 (10NOS2−/−)." (PMID 25210773, 2014). "IL-10 was also increased in the culture supernatants of lepromatous as compared to tuberculoid leprosy patients (p<0.02) In general, increase in FOXP3+ cells in leprosy is in agreement with other studies in leprosy; however there are differences in the nature of cytokine associated with them." (PMID 24454972, 2014). "Thus, besides the higher levels of IP-10, also the shorter whole blood assay time required render IP-10 combined with ML2478 or as ratio with IL-10 directly in serum, a preferred pro-inflammatory biomarker to discriminate between leprosy patients and EC." (PMID 24810599, 2014). "In the evaluation of IL-10 in the plasma from patients was observed that it was increased only in the group of patients with the PB form, differently from what has been described in the literature, which reports an increase mainly in MB forms and leprosy reactions." (PMID 38381878, 2024). "In fact, the role of Th9 lymphocytes in leprosy was evaluated in a study that demonstrated higher levels of IL-9 in the tuberculoid pole, explained by the antagonistic function of IL-9 in relation to IL-4 and IL-10, changing the immune response from the Th2 to the Th1 pole." (PMID 35379512, 2022). "IL10 plays key role in different diseases, such as; hepatitis B, pulmonary tuberculosis, herpes zoster, cutaneous malignant melanoma, skin squamous cell carcinoma, inflammatory bowel diseases, human immuno deficiency viruses (HIV), leprosy, schistosomiasis, malaria, filaria and rheumatoid arthritis." (PMID 25941808, 2015). "Therefore, we evaluated ML-specific TNF/IL-10 ratio, and the results confirmed a high ratio between production levels of these cytokines in relapse leprosy compared to all other assessed groups, especially newly diagnosed and untreated MB patients (ratio 59:9; p< 0.001)." (PMID 25992795, 2015). "Interestingly, IL-10 is also detected in paucibacillary leprosy lesions." (PMID 25210773, 2014). "The action of IL-10 in leprosy lesions leads to the differentiation of regulatory CD4+ T cells, as well as regulatory B cells that produce high levels of IL-10." (PMID 38381878, 2024). "We investigated the production of IL-10 by PD-1neg and PD-1+ Treg cells in stimulated PBMC cultures of leprosy patients and healthy controls that were treated with M. leprae antigen." (PMID 37153623, 2023). "Treg cell suppression is mediated by inhibitory cytokines such as IL10, IL-35 and TGF-β and its frequency is higher in leprosy patients." (PMID 37153623, 2023). "Short-term cultures in vitro of peripheral blood mononuclear cells from leprosy patients and healthy Controls were carried out to quantify the percentages of cytokine+ cells (IFN-γ, IL-4 and IL-10) amongst T-cells, CD4+ T-cells and CD8+ T-cells." (PMID 33341111, 2020). "We also observed the simmiler pattern of IL-10 production by CD4+CD25– cells in various genotypes (CC, CT and TT) of leprosy patients." (PMID 32849660, 2020). "Our data demonstrated that leprosy patients presented an overall polyfunctional profile of T-cells subsets, with increased frequency of IFN-γ+ T-cell subsets along with IL-10+ and IL-4+ from CD4+ T-cells." (PMID 33341111, 2020). "We found an increased frequency of Bregs and increased expression of their immune modulatory molecules (IL-10, FoxP3, and PDL-1) in leprosy patients." (PMID 30083152, 2018). "Our results show an increase in IL-10+ Bregs and PDL-1 expression in in vitro antigen induced peripheral blood mononuclear cell (PBMCs) of leprosy patients." (PMID 30083152, 2018).
leprosy (continued). "TGF-β is known to induce FoxP3 expression in Tregs and others immune cells and high TGF-β level has been reported in leprosy patients, thus we examined the FoxP3 expression in CD19+IL-10+ cells derived from leprosy patients and healthy controls." (PMID 30083152, 2018). "In a leprosy model, IFN-γ differentially modulated IL-12 and IL-10 production resulting in up-regulation of IL-12 and down-regulation of IL-10 release in response to Mycobacterium leprae stimulation." (PMID 25889716, 2015). "We found that three soluble mediators (CCL17, CCL18 and IL10) and one cell marker (CD14) were differentially expressed in leprosy dermal lesions." (PMID 25412496, 2014). "The mean values for IL-10 cytokine in a leprosy patient’s STH -positive and negative groups were 66.03 pg./ml and 76.46 pg./ml, respectively, showing no significant (p>0.41) difference between the groups." (PMID 40636115, 2025). "A higher number of Tregs were observed in leprosy patients, who expressed increased levels of IL-10 and CTLA-4 but not TGF-β." (PMID 37153623, 2023). "The cytokine signature analysis demonstrated that leprosy patients presented a polyfunctional profile of T-cells subsets, with increased frequency of IFN-γ+ T-cell subsets along with IL-10+ and IL-4+ from CD4+ T-cells, as compared to health Controls (Venn diagram report)." (PMID 33341111, 2020). "The differential expression among TLRs in the leprosy reaction groups, T1R and ENL, hypothetically suggests that the TLR2/2 homodimer formation may mediate the production of IL-10." (PMID 31781675, 2019). "Role of IL-10 in induction of phagocytic programme in macrophages but not triggering antimicrobial pathway in leprosy has been earlier reported." (PMID 30642265, 2019). "Although the ligand for LILRA2 has not been identified, its activation inhibits TLR2/1-induced IL-12 release but maintains IL-10 release, and while the mechanism of LILRA2 activation during leprosy remains uncertain, LILRA2 is notably more highly expressed in LL than in TT lesions." (PMID 28162092, 2017). "For leprosy reactions, the most common proinflammatory mediators were TNF-α (7 articles), IFN-γ (5 articles), IL-6 (4 articles), and IL-17 (3 articles), and the most common anti-inflammatory mediators were IL-4 (4 articles) and IL-10 (4 articles)." (PMID 26339136, 2015). "A recent elegant experimental study suggested that the interaction between IL-10 and inducible nitric oxide synthase (NOS) may be responsible for the reactivity of antigen-specific T lymphocytes responses related to leprosy neural damage." (PMID 25992795, 2015). "To accommodate ELISAs to field-applicable tests for leprosy diagnosis, we previously developed UCP-LFAs for detection of IFN-γ and IL-10 as well as antibodies against the M. leprae-specific phenolic glycolipid-I (PGL-I) for high-tech, laboratory-based microtiter-plate readers." (PMID 24810599, 2014). "Relatedly, another valuable observation made here was the significant difference in IP-10/IL-10 ratios in sera of leprosy patients and EC, even without antigen stimulation." (PMID 24810599, 2014). "Interestingly, our study demonstrated that CCL17 and CCL18 distinguished leprosy polarity with greater accuracy than the traditional TH1 and TH2 cytokines (IL10, IFNG)." (PMID 25412496, 2014). "Other mRNAs were also less expressed in leprosy patients when compared to non-leprous samples, such as Bad, IL10, IL12 as well as several mitochondrial genes (mtCOX2, mtND1, mtND3 mtND5 mtATP6, and mtCYB)." (PMID 23798993, 2013). "While Tuberculoid (TT) or Paucibacillary (PB) leprosy patients show a Th1 immune profile with higher levels of interleukin-2 (IL-2) and interferon-γ (IFN-γ), lepromatous (LL) or multibacillary (MB) patients exhibit a Th2 immune profile with the rise in IL-10 and IL-4 interleukins." (PMID 40636115, 2025).
leprosy (continued). "Despite proper standardization of IL-10 staining in positive control samples from human intestine which were run in parallel, no IL-10 staining was seen in leprosy T1R or T2R or reaction-free lesions, while adequate staining for TGF-β, IL-17 and IFN-γ was achieved in leprosy lesions." (PMID 29883464, 2018). "The higher frequency of CD19+IL-10+ Breg cells with increased expression of FoxP3 and PDL-1 on Bregs suggests that increased in FoxP3 and PDL-1 expression by the Breg cells might be instrumental in dampening of the T cell function in leprosy patients." (PMID 30083152, 2018). "Moreover, anti-PGL-I IgM levels could not be used to discriminate PB patients or (BCG-vaccinated) HHC from EC, which clearly demonstrates the added value of IP-10, IL-10 and CCL4 in leprosy diagnostics." (PMID 27682181, 2016). "As high-tech laboratories are often lacking in leprosy endemic areas, we examined the diagnostic potential of earlier developed field-friendly UCP-LFAs for detection of anti-PGL-I IgM antibodies and cyto/chemokines IP-10, IL-10 and CCL424, 28, 31, in an extensive cohort in Bangladesh." (PMID 27682181, 2016). "In fact, the low levels of IL-10 production in response to ML-stimulated PBMC in our relapsed group may be due to the phase of the infection and the diagnosis, where low levels of this cytokine can modulate the chronic inflammatory state, as observed in the lepromatous leprosy patients." (PMID 25992795, 2015). "In this systematic review, we identified important pro- and anti-inflammatory mediators involved in the occurrence of dental infections and leprosy reactions, including IL-6, IFN-γ, TNF-α, IL-1β, IL-17, IL-10, and IL-4, which were independent of the laboratory technique and sample." (PMID 26339136, 2015).